RNA5SP528 (RNA, 5S ribosomal pseudogene 528)
Gene: Ribosomal RNA gene on chromosome 20 (30,816,156 to 30,816,274, reverse strand). Ensembl gene ENSG00000275305.
Homologues: Orthologues: chimpanzee 5S_rRNA (97% identical), macaque 5S_rRNA (83% identical), guinea pig 5S_rRNA (62% identical). Paralogues in human: 5S_rRNA (92% identical), RNA5SP530 (91% identical), RNA5SP532 (91% identical), RNA5S1 (86% identical), RNA5S10 (86% identical), RNA5S11 (86% identical), RNA5S12 (86% identical), RNA5S13 (86% identical), RNA5S14 (86% identical), RNA5S15 (86% identical), RNA5S16 (86% identical), RNA5S17 (86% identical), and 26 more.